AGBL1 (AGBL carboxypeptidase 1)
Description:
Metallocarboxypeptidase that mediates deglutamylation of tubulin and non-tubulin target proteins. Catalyzes the removal of polyglutamate side chains present on the gamma-carboxyl group of glutamate residues within the C-terminal tail of tubulin protein. Specifically cleaves tubulin long-side-chains, while it is not able to remove the branching point glutamate. Also catalyzes the removal of polyglutamate residues from the carboxy-terminus of non-tubulin proteins such as MYLK.
Synonyms: CCP4; FLJ32310; FECD8
Tractability: PROTAC: its protein half-life has been measured.
Gene: Protein-coding gene on chromosome 15 (86,079,871 to 87,049,169, forward strand). Ensembl gene ENSG00000273540.
Subcellular location: Cytoplasm, cytosol
Pathways (Reactome):
Metabolism of proteins: Carboxyterminal post-translational modifications of tubulin
Gene Ontology:
Molecular function: metallocarboxypeptidase activity; tubulin binding; zinc ion binding
Biological process: proteolysis
Cellular component: cytoplasm; microtubule cytoskeleton; cytosol
Genetic constraint (gnomAD): Loss-of-function variants: 121 observed, 107.2 expected, observed/expected ratio (o/e) 1.13, 90% interval 0.97 to 1.31. The upper end of that interval is the gene's LOEUF score, 1.31, which puts it in group 5 of 6, group 1 being the genes least tolerant of losing a copy. Missense variants: 1,539 observed, 1,281.7 expected, observed/expected ratio (o/e) 1.2, 90% interval 1.15 to 1.25. Synonymous variants: 547 observed, 474.75 expected, observed/expected ratio (o/e) 1.15, 90% interval 1.07 to 1.24.
Homologues: Orthologues: chimpanzee AGBL1 (93% identical), macaque AGBL1 (90% identical), pig AGBL1 (81% identical), dog AGBL1 (79% identical), mouse Agbl1 (77% identical), rat Agbl1 (77% identical), guinea pig AGBL1 (77% identical), rabbit AGBL1 (71% identical), tropical clawed frog agbl1 (54% identical), zebrafish agbl1 (46% identical). Paralogues in human: AGTPBP1 (46% identical), AGBL2 (20% identical), AGBL3 (19% identical), AGBL4 (14% identical), AGBL5 (13% identical).
Diseases named in the same sentence as AGBL1 in open-access papers:
AGBL1 is named in the same sentence as 29 diseases in open-access papers, as found by Europe PMC text mining. Sharing a sentence is not in itself a finding about the gene and the disease. The quoted sentences say what the papers report.
Fuchs endothelial corneal dystrophy (5 papers, 2019 to 2024). Fuchs endothelial corneal dystrophy (FECD) is the most frequent form of posterior corneal dystrophy (see this term) and is characterized by excrescences on a thickened Descemet membrane (corneal guttae), generalized corneal edema, with gradually decreased visual acuity. "In this review, we first summarized the mutations of COL8A2, TCF4, TCF8, SLC4A11 and AGBL1 genes in Fuchs endothelial corneal dystrophy." (PMID 34130750, 2021). "Similarly, variants in ZEB1, COL8A2, TCF4, FEN1, AGBL1, and LOXHD1 all cause Fuchs endothelial corneal dystrophy (FECD), while the age of onset may vary." (PMID 31555324, 2019). "The authors suggest that TCF4 may be an enzymatic target of AGBL1 and this interaction could potentially explain the development of Fuchs endothelial corneal dystrophy (FECD)." (PMID 38340174, 2024).
Fuchs corneal dystrophy (3 papers, 2018 to 2025). "Mutations of the AGBL1 gene are associated with late-onset of Fuchs’ corneal dystrophy, an autosomal dominant condition that results in corneal epithelial destruction." (PMID 32935225, 2020).
lung carcinoma (2 papers, 2021 to 2025). "The Mzb1 played an important role in antibody secretion while polymorphism of rs4513061 in Agbl1 was linked to lower lung cancer risk." (PMID 40437524, 2025). "Moreover, rs11638062 is located in the AGBL1 gene, polymorphism in which was also associated with lung cancer risk in the Chinese population, suggesting its potential role on tumorigenesis." (PMID 33891562, 2021).
schizophrenia (2 papers, 2023 to 2024). A major psychotic disorder characterized by abnormalities in the perception or expression of reality. "An analysis in the Russian population identified the AGBL1 gene as being linked to schizophrenia and cognitive abnormalities, characterized by tubulin glutamylation effects, which signifies its involvement in neuropsychiatric disorders." (PMID 39202552, 2024). "An analysis of the available literature on the AGBL1 gene showed that the association between AGBL1 and some phenotypes was reported for the risk of coronary artery disease, carotid plaque, specific learning disorders, and cognitive endophenotypes of schizophrenia." (PMID 37441688, 2023).
depression (1 paper, 2019). "GWAS for the HGA/GR ratio identified two genetic loci that mapped to the TAC1 and ASNS genes, which are known to be involved in depression and neurotransmission, while the ratio MET/TYR identified the gene AGBL1 previously linked to neurodegeneration in mice." (PMID 31273200, 2019).
hepatocellular carcinoma (1 paper, 2016). A malignant tumor that arises from hepatocytes. "Interestingly, in hepatocellular carcinoma, lnc-AGBL1-4 has been demonstrated to regulate the expression of NTRK3 by miR-128 and miR-485-3p to strengthen cell invasion and migration." (PMID 27916857, 2016).
AGBL1 also shares sentences with these, for which no sentence is quoted: congenital stromal corneal dystrophy (2 papers); brittle cornea syndrome (1); carcinoma (1); Charcot-Marie-Tooth disease, type 6 (1); cognitive abnormalities (1); connective tissue diseases (1); coronary artery disease (1); COVID-19 (1); dense deposit disease (1); Endothelial dystrophies (1); fleck corneal dystrophy (1); gelatinous drop-like corneal dystrophy (1); hereditary corneal dystrophies (1); ischemic stroke (1); learning disorders (1); macular corneal dystrophy (1); neuroblastoma (1); Obesity (1); optic atrophy (1); posterior polymorphous corneal dystrophy (1); Schnyder corneal dystrophy (1); tumour (1); type 2 diabetes mellitus (1).